ENSG00000286165 (novel protein)
Gene: Protein-coding gene on chromosome 2 (189,661,519 to 189,667,881, forward strand). Ensembl gene ENSG00000286165.
Genetic constraint (gnomAD): Loss-of-function variants: 12 observed, 17.65 expected, observed/expected ratio (o/e) 0.68, 90% interval 0.44 to 1.1. Missense variants: 189 observed, 221.04 expected, observed/expected ratio (o/e) 0.86, 90% interval 0.76 to 0.96. Synonymous variants: 71 observed, 74.07 expected, observed/expected ratio (o/e) 0.96, 90% interval 0.79 to 1.17.